IGLV3-16 (immunoglobulin lambda variable 3-16)
Description:
V region of the variable domain of immunoglobulin light chains that participates in the antigen recognition. Immunoglobulins, also known as antibodies, are membrane-bound or secreted glycoproteins produced by B lymphocytes. In the recognition phase of humoral immunity, the membrane-bound immunoglobulins serve as receptors which, upon binding of a specific antigen, trigger the clonal expansion and differentiation of B lymphocytes into immunoglobulins-secreting plasma cells. Secreted immunoglobulins mediate the effector phase of humoral immunity, which results in the elimination of bound antigens. The antigen binding site is formed by the variable domain of one heavy chain, together with that of its associated light chain. Thus, each immunoglobulin has two antigen binding sites with remarkable affinity for a particular antigen. The variable domains are assembled by a process called V-(D)-J rearrangement and can then be subjected to somatic hypermutations which, after exposure to antigen and selection, allow affinity maturation for a particular antigen.
Synonyms: IGLV316; V2-11
Gene: Immunoglobulin variable (V) gene on chromosome 22 (22,747,383 to 22,747,921, forward strand). Ensembl gene ENSG00000211665.
Subcellular location: Secreted; Cell membrane
Gene Ontology:
Biological process: immune response
Cellular component: extracellular region; immunoglobulin complex; plasma membrane
Homologues: Orthologues: tropical clawed frog igl (51% identical). Paralogues in human: IGLV3-25 (91% identical), IGLV3-10 (84% identical), IGLV3-27 (81% identical), IGLV3-1 (75% identical), IGLV3-22 (72% identical), IGLV3-9 (70% identical), IGLV3-19 (69% identical), IGLV3-12 (68% identical), IGLV3-21 (68% identical), IGLV3-32 (64% identical), IGLV1-40 (58% identical), IGLV2-18 (57% identical), and 81 more.
Diseases named in the same sentence as IGLV3-16 in open-access papers:
IGLV3-16 is named in the same sentence as 1 disease in open-access papers, as found by Europe PMC text mining. Sharing a sentence is not in itself a finding about the gene and the disease.
IGLV3-16 shares sentences with these, for which no sentence is quoted: COVID-19 (1 paper).